MUC2 (mucin 2, oligomeric mucus/gel-forming)
Diseases named in the same sentence as MUC2 in open-access papers (continued):
Sharing a sentence is not in itself a finding about the gene and the disease.
Chronic colitis (15 papers, 2014 to 2026). A chronic inflammatory disease of the large intestine (colon, cecum and rectum). "In Winnie mice, spontaneous chronic colitis results from a primary intestinal epithelial defect conferred by a missense mutation in the Muc2 mucin gene." (PMID 32784883, 2020). "Spontaneous chronic colitis in Winnie mice is the consequence of a missense mutation in the mucin MUC2 gene." (PMID 32998266, 2020). "The beneficial effects of idebenone in this model of spontaneous chronic colitis were associated with the suppression of ER stress, the restoration of MUC2 expression and the simultaneous reduction of increased levels of pro-inflammatory cytokines." (PMID 32998266, 2020). "We therefore assessed skeletal muscle mass, fiber morphology, and voluntary wheel-running performance in Winnie mice-a spontaneous Muc2 mutant model of chronic colitis-in separate female and male homozygous mutant and WT littermate cohorts." (PMID 42201141, 2026). "Here we use Muc2 knockout mouse model of chronic colitis to uncouple the effects of the intestinal microbiota on host behavior from chronic inflammation in the gut." (PMID 36175462, 2022). "In order to understand the interrelation between chronic colitis, microbiota and CNS function, we utilized Mucin 2 (Muc2) knockout mice as a well-described model of intestinal inflammation." (PMID 36175462, 2022). "There was also higher bacterial growth in the serum of Muc2+/+ littermates after induction of chronic colitis by continuous low dose DSS." (PMID 31980623, 2020). "Interestingly, the levels of Muc1 and Muc2 increased significantly during remission of chronic colitis, indicating that the synthesis of epithelial mucin was activated during remission." (PMID 36176029, 2022). "Consistent with this, in the IL-10−/− chronic colitis model, Spry2 is elevated in colonic homogenates from adult animals with active inflammation versus young (pre-colitic) littermates, and these mice express reduced levels of tuft (Trpm5) and goblet cell (Muc2) markers in the distal colon." (PMID 33547321, 2021). "Moreover, in mice, Muc2 Knock-Out leads to spontaneous appearance of chronic colitis." (PMID 33051755, 2020). "In another DSS-induced chronic colitis model, both LF ST36 EA and HF ST36 EA increased the level of colonic proteins ZO-1, Occludin, E-cadherin, and MUC2, and this finding showed that EA can protect the mucus layer from bacteria penetration." (PMID 35095910, 2021).
Crohn disease (15 papers, 2006 to 2025). A gastrointestinal disorder characterized by chronic inflammation involving all layers of the intestinal wall, noncaseating granulomas affecting the intestinal wall and regional lymph nodes, and transmural fibrosis. "Although not a significant eQTL on GTEx, the missense variant 11825977 (also known as V116M) has been linked to reduced mRNA expression of MUC2 and increased risk of Crohn's disease." (PMID 33328979, 2020). "On the one hand, R. gnavus could just be a bystander as mucus-degrading bacteria, profiting from mucus changes in inflammatory conditions, such as increased mucus thickness and upregulation of Muc2 secretion, which have both been described for Crohn’s disease." (PMID 31275292, 2019). "Another study recently confirmed that differential expression of mucus production gene (MUC2) is observed in organoids from IBD patients, and in particular from Crohn’s disease patients, compared to controls." (PMID 32582690, 2020).
asthma (14 papers, 2012 to 2025). "Whilst intestinal goblet cell/MUC2 expression is yet to be investigated in ILDs, goblet cell hyperplasia in the lung is a common feature in both asthma and COPD." (PMID 36322182, 2023). "Increased secretion of MUC-2 was also observed in the metaplastic epithelium of airways, in chronic pulmonary diseases (asthma, COPD, cystic fibrosis) and lung cancers." (PMID 36648870, 2022). "MUC-2 expression by glands in the respiratory system is detected in diseases like asthma, cystic fibrosis, COPD, chronic bronchitis, metaplasia and dysplasia." (PMID 36648870, 2022). "The significant signal at MUC2 in our analysis was not independent of the previously reported moderate-to-severe asthma signal for which MUC5AC was implicated as the most likely causal gene using gene expression data from bronchial epithelial cells." (PMID 37263751, 2023). "In our study, we examined the expression levels of critical members of the mucin family, specifically the secreted mucins MUC5AC and MUC5B, in addition to the membrane-bound mucins (MUC1, MUC4, and MUC2) in lung tissue obtained from the TIMPKO murine asthma model." (PMID 34221020, 2021). "There was a trend towards longer MUC2 TR alleles in the asthma and wheeze groups, but this was not statistically significant." (PMID 23551418, 2013). "A polymorphism in MUC2 was linked to asthma, but because MUC2 is not a major airway mucin it was speculated that the variant may be related to a haplotype encompassing airway-related MUC5AC." (PMID 34332619, 2021). "In addition, the secretion of MUC2 in asthma is also significantly increased, and because MUC2 is highly insoluble, even a small amount of MUC2 may lead to excessive airway mucus viscosity and airway obstruction in asthma." (PMID 32620122, 2020). "Among them, MUC5AC is proved to be the major subfamily, and overproduction of airway mucins (especially MUC5AC or mucin-2 (MUC2)) is signature of human asthma and murine models of asthma." (PMID 31330806, 2019). "Many other pathways were also identified that are regulated by IL-13 and relevant to asthma pathogenesis (e.g. CCL17, CCL26, CTGF, FCER1A, KITLG, MUC2, NOS2, TLR3)." (PMID 29367592, 2018). "The specific role of MUC2 expressed in the intestine in the context of asthma is not yet well established." (PMID 40292217, 2025). "The hypersecretion of airway mucus is an important physiological and clinical symptom of various respiratory tract diseases, such as chronic bronchitis and asthma, and airway stimuli, such as antigens, bacteria, and particles, upregulate the MUC5AC and MUC2 genes." (PMID 37687271, 2023).
pancreatic cancer (13 papers, 2008 to 2025). "Among the mucins, expression of MUC5AC is associated with PanINs and all stages of pancreatic cancer, and a low frequency of MUC2 expression is associated with cystic lesions." (PMID 33915081, 2021). "The authors performed a pyrosequencing assay for KRAS (codon 12) mutations and immunohistochemistry for MUC1/MUC2, and compared the histological diagnosis of the initial tumor and the remnant pancreatic cancer in the resected group." (PMID 33805716, 2021). "The abnormalities of MUC2 is linked with colorectal and pancreas cancer." (PMID 21172017, 2010). "Of these proteins, the levels of pancreatic cancer-associated proteins, such as MUC5AC, MUC2, and CEA, were high." (PMID 32842508, 2020). "MSE also showed that intestinal type-IPMNs have a significantly higher U-index for MUC2 compared to other pancreatic neoplasms and that this can be used to identify intestinal-type IPMNs." (PMID 24714692, 2014). "Our research suggested that AZD5153 may be a predictive GEM-sensitive drug in pancreatic cancer, and MUC2 may be serving as a key target in this progress." (PMID 40859234, 2025). "Xenograft tissue staining showed the expression of markers found in some types of pancreatic cancers (ECAD, MUC2 and MUC4), as well as of the pan-cancer cytokeratin CK18, to various degrees." (PMID 39123450, 2024). "Found a 7 gene panel (MDR1, SRBC, VHL, MUC2, RB1, SYK, and GPC3) that detects colorectal and pancreatic cancers with 63.16% sensitivity, 84% specificity, and AUC of 0.8177." (PMID 36980276, 2023). "Since MUC1, MUC2 and MUC4 are key mucins in pathological diagnosis of pancreatic neoplasms, our goal is to apply DNA methylation analysis of the three mucin genes using pancreatic juice for early diagnosis of these neoplasms." (PMID 24714692, 2014). "Recently, methylated CpG mapping of MUC2 and MUC5AC promoters have been determined in pancreatic cancer cell lines." (PMID 24281201, 2010). "Analyses of the DNA methylation status of MUC1, MUC2 and MUC4 were useful for differential diagnosis of human pancreatic neoplasms, with specificity and sensitivity of 87% and 80% for PDAC; 100% and 88% for intestinal-type IPMN; and 88% and 77% for gastric-type IPMN, respectively." (PMID 24714692, 2014). "In our present study, analyses of the DNA methylation status of MUC1, MUC2 and MUC4 in pancreatic juices were useful for differential diagnosis of human pancreatic neoplasms i.e. PDAC, intestinal-type IPMN and gastric-type IPMN, with high specificity and sensitivity." (PMID 24714692, 2014). "Expression of MUC2 mRNA has been correlated with methylation of the proximal region of the promoter in pancreatic cancer cells whereas no direct link was found between methylation and MUC5AC expression." (PMID 24281201, 2010).
colon adenocarcinoma (12 papers, 2006 to 2025). "Although MUC2 expression is decreased both at the transcript and translation levels of colonic adenocarcinoma, its over or ectopic expression of MUC2 is observed in colonic mucinous carcinomas." (PMID 32168759, 2020). "Bacteria may increase MUC2 expression and upregulate pro-inflammatory cytokines that drive mucin production, as seen in human colonic adenocarcinoma cells incubated with F. nucleatum." (PMID 36982838, 2023). "A consistent fraction of these mucins is associated with diseased states, i.e., colon adenocarcinoma (MUC1, MUC2, MUC4, MUC5A/B/C), breast and uterine cancers (MUC1), and lung diseases, which may cause bronchiectasis (MUC)." (PMID 27406561, 2016). "In HM3 colon adenocarcinoma cells, DCA activates the EGFR/Ras/Raf-1/ERK signaling pathway, resulting in the upregulation of mucin 2 (MUC2)." (PMID 39948481, 2025). "Regarding immunohistochemistry, adenocarcinoma of the urinary bladder expresses CEA, CDX-2, MUC-1, MUC-2 and MUC-3, same as colonic adenocarcinoma." (PMID 20205820, 2010). "Intriguingly, LTD4 can also activate MUC2 via transcriptional regulation in colon adenocarcinoma; nevertheless, whether pranlukast overcomes CCRT resistance through MUC2 downregulation in rectal cancer deserves further investigation." (PMID 34300195, 2021). "Ninety per cent of metastatic colonic adenocarcinomas expressed MUC2, but none expressed MUC5AC." (PMID 31689847, 2019).
colorectal adenocarcinoma (12 papers, 2006 to 2025). The most common type of colorectal carcinoma. "To examine intestinal differentiation in colorectal adenocarcinoma, we used markers β-catenin and MUC2." (PMID 39337548, 2024). "A study with a human colorectal adenocarcinoma cell line suggested that polyphenols can modulate the expression of MUC-2 and ZO-1, protecting the epithelial barrier function of cells exposed to a chemical agent." (PMID 36771677, 2023). "The results of some studies have shown that the expression of MUC2 in colorectal adenocarcinomas is reduced [101011], but other studies have shown that its expression is increased." (PMID 35572847, 2021). "Similarly, MUC2 is less expressed in colorectal adenocarcinoma, while its expression is maintained in normal tissue adjacent to the malignancy." (PMID 23874993, 2013).
mucinous tumor (12 papers, 2017 to 2025). "Mucinous tumours overexpress MUC2, a secreted gel-forming mucin that is encoded in the MUC2, MUC5AC, MUC5B and MUC6 genes on chromosome 11." (PMID 36982838, 2023). "Surprisingly, another group showed that dual MEK‐PI3K inhibitor therapy somehow significantly reduced KRAS mutated mucin 2 (MUC2) expression, MUC2 palmitoylation, and secretion in colon cells, ultimately suppressing mucinous tumor growth in vivo." (PMID 36018061, 2023). "Our studies thus provide a rational basis for MEK- and PI3K-targeted combination therapy for not only KRAS mutant MCA but also for other related mucinous neoplasms that overproduce MUC2 and have a high rate of KRAS mutations such as pseudomyxoma peritonei." (PMID 28640835, 2017). "Our data on MUC2 and MUC5AC expression in mucinous tumors were similar to the literature with low expression for MUC2 (2/13) and high expression (11/13) for MUC5AC." (PMID 36367122, 2023). "We feel that these clinically relevant models are especially important for mucinous tumors for which availability of high‐mucin (MUC2) secreting cell lines is limited." (PMID 31958897, 2020). "Targeting MUC2 as a novel therapeutic strategy has been reported to inhibit mucinous tumor growth and improve survival in a murine xenograft model of pseudomyxoma peritonei." (PMID 29786668, 2018). "Here, we report the effectiveness of combinatorial targeting of two KRAS-mediated parallel pathways in reducing MUC2 production and mucinous tumor growth in vitro and in vivo." (PMID 28640835, 2017). "We also provide a mechanistic rationale for using the FDA approved drug celecoxib to inhibit MUC2 protein production and mucinous tumor growth." (PMID 29290997, 2017). "We have previously published promising preclinical data demonstrating effective reduction of MAPK pathway-mediated MUC2 protein production and mucinous tumor growth in vitro and in vivo following treatment with MEK (MAP kinase/ERK kinase) inhibitors." (PMID 29290997, 2017). "Chronic oral administration of celecoxib decreased mucinous tumor growth in our in vivo PMP model via a combination of MUC2 inhibition and induction of apoptosis." (PMID 29290997, 2017). "There was a significant decrease in MUC2 expression suggesting an effective mucinous tumour growth suppression which may be an effective therapy in these patients." (PMID 36723696, 2023). "Treatment with celecoxib effectively reduced mucinous tumor growth inhibition in vivo, supporting our hypothesis that mucinous tumors may be especially vulnerable to a therapeutic strategy that simultaneously suppresses MUC2 suppression and induces apoptosis." (PMID 29290997, 2017). "We hypothesized that simultaneous MUC2 inhibition and apoptosis induction would be effective against mucinous tumors." (PMID 29290997, 2017). "Moreover, we provided a preclinical rationale for the use of celecoxib to suppress mucinous tumor growth since it simultaneously inhibited cAMP/PKA/CREB-mediated MUC2 production and induced apoptosis." (PMID 29290997, 2017). "MUC2 overexpression or ectopic expression is a common property of all mucinous carcinomas including that of the ovary, breast, pancreas and PMP suggesting a common genetic alteration associated with the mucinous tumor phenotype." (PMID 28640835, 2017). "Moreover, we provided promising preclinical data to support the use of celecoxib to decrease mucinous tumor growth in vivo, as a result of its ability to simultaneously suppress MUC2 production and promote apoptosis." (PMID 29290997, 2017). "For instance, immunohistochemical markers like CK7, CK20, Villin, CDX-2, MUC-2, and PAX8 are employed for the differential diagnosis of ovarian primary mucinous neoplasms (OPMN) and ovarian secondary peritoneal pseudomyxoma." (PMID 40486880, 2025). "Our rationale for utilizing orlistat was that it inhibits FASN (required for MUC2 secretion) which would induce ERS, while at the same time reducing mucinous tumor growth." (PMID 32811515, 2020).
mucinous tumor (continued). "This is due to evidence suggesting that the increased MUC2 expression in high-grade PMP is due to a greater number of mucinous tumour cells rather than gene overexpression at a cellular level." (PMID 40599846, 2025).
intestinal infection (11 papers, 2010 to 2026). "Intestinal infections caused by bacteria, viruses, and harmful chemicals can affect goblet cell responses and MUC-2 production, disrupting the intestinal mucosal barrier." (PMID 38672890, 2024). "The reduction in MUC2 levels is generally associated with the loss of the intestinal barrier, increasing the risk of inflammatory processes and intestinal infections." (PMID 38399722, 2024). "The gut mucosal barrier is the first host defense against intestinal infection by E. histolytica, as previously shown in MUC-2-deficient mice." (PMID 28817707, 2017). "We further investigated the colonic barrier function in piglets and found that FMT increased levels of colonic tight junction proteins and expression of the mucin MUC-2 gene, thereby enhancing intestinal barrier function and reducing the risk of intestinal infection and inflammation." (PMID 41545905, 2026). "The effects on MUC1 and MUC2 suggest that specific ENM may lead to an elevated susceptibility towards intestinal infections and inflammations." (PMID 34685068, 2021). "The prebiotic intervention induced a reduction in the levels of MUC2 gene expression, in agreement with a reduction also observed in a gastrointestinal infection model in suckling rats supplemented with this prebiotic mixture." (PMID 34578853, 2021). "The importance of the constitutive expression of mucins has been highlighted by mouse models deficient of MUC1, MUC2, and MUC13, revealing elevated susceptibilities towards intestinal infections, inflammations and spontaneous tumors." (PMID 34685068, 2021). "Yet, further research is required to clarify whether the alterations of MUC1, MUC2 and MUC13 expression are physiologically relevant for the susceptibility towards intestinal infections and inflammations." (PMID 34685068, 2021). "Moreover, in WT mice, although not the main mucin (which is Muc2), for the first time in a nematode infection we show the up-regulation of Muc5ac after intestinal infection." (PMID 20138044, 2010).